NRAS (NRAS proto-oncogene, GTPase)
Diseases named in the same sentence as NRAS in open-access papers (continued):
Sharing a sentence is not in itself a finding about the gene and the disease.
melanoma (continued). "Sequencing of mutation hotspots in five melanoma driver genes (BRAF, NRAS, KRAS, GNAQ, GNA11) did not reveal any changes in 9/11 patients." (PMID 30558566, 2018). "Also, oncogenic NRAS and HRAS increase GLI1 function in melanoma cells, and HH-GLI signaling is required for NRAS-induced mouse melanoma growth." (PMID 30158435, 2018). "Similar effects were noted in both NRAS and BRAF mutant melanoma cells following Ets-1 or Usp9x KD." (PMID 28198367, 2017). "Thus, some NRAS and BRAF mutant melanomas were sensitive to the EPE peptide, while others were either partially sensitive or not sensitive at all." (PMID 29180761, 2017). "Usp9x KD reduced the stability of Ets-1 in both BRAF and NRAS mutant melanoma and decreased NRAS, but not total RAS protein levels." (PMID 28198367, 2017). "Polysomy of NRAS/chromosome 1 was detected in 13.3% (4/30) of HET, and 28.6% (6/21) of High non-HET samples, but was absent in BRAF/NRAS WT melanomas (P < 0.05)." (PMID 28668077, 2017). "In this study, we found that the EPE peptide also reduces the viability of NRAS and some NF1 mutant melanomas as well, and combination of EPE peptide and MEK inhibitor trametinib showed synergy in reducing the growth of other melanomas, including those resistant to each drug alone." (PMID 29180761, 2017). "Although it is not clear why NRAS mutations are more frequent in melanoma compared to HRAS or KRAS mutations, there is evidence that NRAS is overexpressed in melanocytes relative to other RAS isoforms." (PMID 29349077, 2017). "The role of ARAF in NRAS-induced melanoma has not been a matter of intense investigation mainly because of the well-described paradoxical effects of RAF inhibitors in RAS-mutated tumours, which is thought to rely mostly on BRAF and CRAF dimerization." (PMID 28497782, 2017). "CJM, HMCB, and CHL1 also lacked mutations in BRAF, NRAS, or NF1, but these cell lines had similar FGA and mutational burden relative to other melanoma cell lines as well as tumors." (PMID 29383127, 2017). "Notably miR-340 is able to affect the expression of 39 out of 45 total RAS-RAF-MAPK components, such as BRAF, KRAS, NRAS and MYC, thus reducing melanoma cell growth and migration." (PMID 28118616, 2017). "The impact on NRAS is however non-uniform, with some NF1 mutant melanomas exhibiting full NRAS activation (i.e. the same activation level as oncogenic NRAS mutations), whereas others exhibit only partial activation." (PMID 28637487, 2017). "In melanoma, both MEK and BRAF inhibition led to an induction of Ets-1 and NRAS expression that could be blocked by Usp9x inhibition." (PMID 28198367, 2017). "One mutated case was a superficial spreading melanoma diagnosed in 1999, that did not display BRAF, NRAS and TERT promoter mutations, and the patient was alive at the last follow-up (180 months)." (PMID 28662141, 2017). "RAS/MAPK pathway dysregulation has been identified as a key culprit in non-familial melanoma, leading to the discovery of BRAF and NRAS as the most commonly mutated genes." (PMID 28637487, 2017). "There was co-incident and significant overexpression of Usp9x, Ets-1 and NRAS in melanoma versus nevi, but Usp9x expression was not notably different between primary and metastatic melanoma." (PMID 28198367, 2017). "Interestingly, the data shown that combination of ABT-737 and 4-HPR significantly eliminate ALDH+ CSCs in multiple melanoma cell lines including BRAF and NRAS mutant cells." (PMID 28137308, 2017). "In 452 patients, 182 (40.3%) melanomas were BRAF-mutant, 95 (21.0%) were NRAS-mutant, and 180 (39.8%) were wild-type (no BRAF mutation and no NRAS mutation); only 5 (1.1%) were both BRAF-mutant and NRAS-mutant." (PMID 29349077, 2017).
melanoma (continued). "To further elucidate the role of Usp9x in melanoma and examine the sensitivity of NRAS mutant tumours to Usp9x KD and inhibition, we first assessed the effects of Usp9x KD on specific RAS proteins in highly metastatic NRAS and BRAF mutant melanomas." (PMID 28198367, 2017). "Although there have been no studies assessing NRAS as a synthetic dose lethal target in melanoma, in acute myeloid leukaemia (AML) the multitarget kinase inhibitor GNF‐7 has been reported to induce apoptosis in NRAS‐mutant but not wild‐type AML." (PMID 28097822, 2017). "The combination increased the level of PARP cleavage relative to the DMSO or either treatment alone in all three relapsed melanoma patient samples tested, irrespective of the mutation status of BRAF or NRAS." (PMID 27829238, 2016). "Moreover, nelfinavir is effective in BRAF and NRAS mutant melanoma cells isolated from patients progressed on MAPK inhibitor (MAPKi) therapy and in BRAF/NRAS/PTEN mutant tumors." (PMID 26977879, 2016). "Regardless of their NRAS status, our observation that MM127 cells cannot be detected using standard melanoma-associated markers is an important finding." (PMID 27087056, 2016). "In summary, we have demonstrated that the combination of GSI-I with ABT-737 killed the bulk and the MICs of multiple melanoma samples, irrespective of the mutational status of BRAF, NRAS or NF-1." (PMID 27829238, 2016). "Both BRAF and NRAS mutations are known to deregulate the MAPK pathway, functioning as mutually exclusive aberrations in melanoma not exposed to BRAF-inhibitors." (PMID 27447557, 2016). "We found a strong inverse correlation between the mRNA expression of ZEB1 and MITF in melanoma cell lines from the Cancer Cell Line Encyclopedia (CCLE), regardless of their BRAF/NRAS mutational status (n = 61, P = 4.08E‐11)." (PMID 27596438, 2016). "To investigate a link between MAPK pathway activation and TERT expression in presence or absence of TERT promoter mutation, we performed experiments on nine melanoma cell lines with or without TERT, BRAF and NRAS mutations." (PMID 27449293, 2016). "Overall, EPHB6G404S mutations were more frequently observed in melanomas without BRAF or NRAS mutations (16/202 melanomas, 7.9%), than co-occurring with either BRAF or NRAS mutations (10/264 melanomas, 3.8%, p-value = 0.04)." (PMID 27191502, 2016). "A miRNA signature specifically associated with melanomagenesis mediated by ARF loss was identified, with miR-32 as one of the top miRNAs upregulated in NRAS-transformed ARF-/- cells; miRNA had not previously been implicated in melanoma." (PMID 27846237, 2016). "Approximately 75% of melanomas have known driver oncogenic mutations in BRAF, NRAS, GNA11 or GNAQ, while the mutations providing constitutive oncogenic signaling in the remaining melanomas are not known." (PMID 27273450, 2016). "Another major drawback of current melanoma treatments is the lack of therapeutic options for patients who are WT for common mutations in BRAF, NRAS or NF-1 (Triple-WT)." (PMID 27829238, 2016). "We defined “pan-negative” samples as those melanomas harboring none of the well-known, specific, and recurrent mutations in the genes BRAF, NRAS, KIT, GNAQ, or GNA11, which are commonly mutated in melanoma." (PMID 25537510, 2015). "Immunohistochemical analysis of BRAF-mutant, NRAS-mutant and pan-negative patient melanomas revealed wide heterogeneity of DUSP4 expression in each subtype." (PMID 26084293, 2015). "The BRAF/NRAS wild-type melanomas, i.e. samples negative for mutations in both BRAF and NRAS, more often had genetic alterations in KIT or NF1 (P < 0.001, Fisher's exact test)." (PMID 25909218, 2015). "Although the most active MEK inhibitors have shown promising activity, none have been FDA-approved for treatment of NRAS-mutant melanoma." (PMID 25537510, 2015).
melanoma (continued). "The melanoma cell lines had various statuses of the most common mutations in BRAF (BRAFV600E) and NRAS (NRASQ61R), but harboured no mutation in the other key components of the PI3K pathway, including PIK3CA, PTEN, and PIB5PA." (PMID 26573229, 2015). "Mutant NRAS was also shown to activate the PI3K/mechanistic target of rapamycin (mTOR)-signaling cascade and combined inhibition of MEK and PI3K was synergistic in certain NRAS mutant cell lines of melanoma, lung cancer and neuroblastoma." (PMID 26544513, 2015). "A previous study of cancer cells not specific to melanoma reported paradoxical activation of MEK1/2 upon MEK1/2 inhibition in a BRAF-/NRAS-wild-type setting, citing that signaling in these cells is regulated by receptor tyrosine kinases (RTKs)." (PMID 26084293, 2015). "NRAS targeting is a new field in melanoma treatment and there is no consensus on the NRAS inhibitors to date." (PMID 26204954, 2015). "Importantly, these analyses were performed in melanocytes expressing HRASG12V, as well as oncogenic forms of NRAS (i.e. NRASG12V or NRASQ61R), the latter being characteristic of congenital nevi and a sizable fraction (about 25%) of melanomas." (PMID 26008978, 2015). "Nevertheless, the effect of zoledronic acid on melanoma cells in vivo and the dependence of biological response on the BRAF or NRAS oncogenic mutation status have not yet been studied." (PMID 25646931, 2015). "Using cell proliferation and DNA methylation assays, FACS analysis and quantitative-RT-PCR we have characterised the response of a panel of NRAS and BRAF mutant melanoma cell lines to various chemotherapy drugs, amongst them dacarbazine (DTIC) and temozolomide (TMZ) and DNA synthesis inhibitors." (PMID 24941944, 2014). "To address the potential influence of the genetic background on the response of melanoma cells to chemotherapeutic agents, we tested three different classes of DNA damaging agents: carmustine, cisplatin and DTIC in 9 NRAS mutant and 9 BRAF mutant melanoma cell lines (mutNRAS and mutBRAF cells)." (PMID 24941944, 2014). "Over 50% of all melanoma patients are non-BRAF mutated, with NRAS-mutant and double wild-type comprising 15-20% and 40% of melanoma patients, respectively." (PMID 25142146, 2014). "From the pathogenetic point of view, the mitogen-activated protein kinase (MAPK) signal transduction pathway (including the cascade of NRAS, BRAF, MEK1/2, and ERK1/2 proteins) has been reported to play a major role in both the development and progression of melanoma." (PMID 24885594, 2014). "Our results demonstrate that in melanoma the presence of mutually exclusive BRAF and NRAS mutations has no influence on the response to DNA alkylating agents such as TMZ." (PMID 24941944, 2014). "Besides the expected coding mutations in BRAF, NRAS, CDKN2A, and other genes detected, significant numbers of recurrent copy number variants and structural rearrangements found in this analysis of 13 WGS cases suggest that they may be important initiating and metastatic events in melanoma." (PMID 25393105, 2014). "While targeting of mutant BRAF with small molecule inhibitors such as vemurafenib and dabrafenib showed promising results in BRAF mutant melanoma, there are no therapeutics available which specifically inhibit mutant NRAS." (PMID 25277205, 2014). "BRAF and NRAS status also had no impact on the disease-free interval from the diagnosis of the primary melanoma to nodal metastases." (PMID 24959217, 2014). "Due to the absence of successful specific RAS inhibitors for the treatment of melanoma, there are currently no registered clinical trials for the evaluation of NRAS inhibitors." (PMID 23515890, 2013). "The phosphorylation patterns in melanoma did however not correlate to any clinical or molecular parameters, like BRAF- and NRAS mutational status, or response to DTIC therapy." (PMID 24023633, 2013).
melanoma (continued). "Due to the heterogeneous genotypic profile in human melanoma, there was no clear relationship between BRAF or NRAS that predicted effects of PRMT5 loss on proliferation." (PMID 24098663, 2013). "Similar to what was seen for BRAF, NRAS expression levels were found to be significantly higher in malignant melanomas than in non-malignant nevi (p = 0.018)." (PMID 23673558, 2013). "Melanoma cells constitutively harbor - besides well-defined mutations in certain proto-oncogenes like BRAF and NRAS - also non-random genomic alterations reflecting chromosomal instability (CIN)." (PMID 22535842, 2012). "Inhibition of this kinase is postulated as an interesting target in BRAF mutant melanoma, but not in NRAS." (PMID 22216021, 2012). "As expected, we found the known melanoma drivers NRAS and BRAF to have the largest numbers of non-synonymous mutations in our candidate list." (PMID 22912864, 2012). "In melanoma, the increased PDE4B2 expression was observed compared with that in melanocyte and PDE4B2 expression is necessary to transform melanocyte with oncogenic NRAS, implicating the effective strategy for cancer treatment by targeting the PDE4B2." (PMID 22830422, 2012). "Curtin and colleagues showed that primary melanomas arising from chronically sun-damages skin and mucosal sites, the latter of which typically do not harbor BRAF and NRAS mutations, have increased CCND1 copy number." (PMID 21479172, 2011). "Apart from NRAS, either deletion of PTEN or overexpression of AKT mainly lead to the stimulation of mTOR, a central regulator of cell growth and proliferation that has raised substantial interest in this signaling pathway in melanoma." (PMID 22007305, 2011). "Interestingly, mutant BRAF, which is present in almost 70% of all melanomas, shows marked dependency on Hsp90 and is degraded by 17-AAG treatment, while WT BRAF activated by NRAS is also Hsp90 dependent." (PMID 21037799, 2010). "Mutations were also identified in brain metastases from non-breast primaries in EGFR (3/9 - 33%; two lung and one kidney), HRAS (1/9 - 11%; lung), KRAS (2/9 - 22%; one colon and one lung), NRAS (3/9 - 33%; two lung and one kidney) and PIK3CA (2/9 - 22%; one melanoma and one lung)." (PMID 20604919, 2010). "Activating mutations in NRAS and β-catenin, or loss of PTEN did not affect the responses of BRAFWT melanoma cells to this BRAF inhibitor." (PMID 20149136, 2010). "Increasing concentrations of PLX4720 (1 h) inhibited pERK signalling in three BRAF-mutated melanoma cell lines (WM35, WM164 and 1205Lu), but not an NRAS-mutated cell line (WM1346)." (PMID 20531415, 2010). "In our hands, the presence of mutant NRAS in BRAFWT melanoma cells was not required for PLX4032 induced ERK activation, cell detachment, loss of adherence and migration." (PMID 20149136, 2010). "It is interesting to note that several studies also suggest the relevance of combined inhibition of CRAF and BRAF in a BRAF mutant context for efficacy and may prove to be relevant strategy for treatment of both NRAS and BRAF mutant melanomas." (PMID 19492075, 2009). "However, the absence of melanoma markers, including HMB45 and Melan-A, and the negative molecular profile for any melanoma-associated genetic alterations, including BRAF, NRAS, and NF1 gene alterations, argued against such an entity." (PMID 40978976, 2025). "This may explain why the MEK inhibitor binimetinib has not been shown to be effective in NRAS mutant melanomas when used as monotherapy." (PMID 40361349, 2025). "Second, the singular focus on KRAS-centric pathways, although justified by emerging evidence of KRAS involvement in some melanomas, may overlook synergistic or compensatory signaling through parallel oncogenic axes such as those governed by BRAF, NRAS, or PI3K-AKT-mTOR." (PMID 40607411, 2025). "No specific NRAS inhibitor has been approved, but promising results have emerged with naporafenib, an inhibitor of KRAS and NRAS-mutated tumors (in lung carcinoma and melanoma)." (PMID 40423070, 2025).
melanoma (continued). "The literature suggests that malignant NCH may be distinct from melanoma based on the lack of GNAQ, NRAS, BRAF, and KIT mutations that are commonly identified in melanoma." (PMID 40265343, 2025). "Unlike melanoma with a BRAF mutation, NRAS mutations are more resilient to treatment." (PMID 39519055, 2024). "Instead, ipilimumab treatment could be of great value in patients with BRAF/NRAS-wildtype melanoma and without brain metastases, with several benefits to long-term survival, although a larger dataset is needed for a more precise indication." (PMID 39410017, 2024). "Notably, melanoma patients with BRAF and NRAS mutations who have failed to respond optimally to agents like anti-PD-1 or anti-CTLA-4 antibodies have exhibited either partial response or long-stable disease (SD) after receiving TIL treatment." (PMID 38835341, 2024). "By contrast, high-CSD melanomas do not harbor BRAF V600E mutations but present other mitogen-activated protein kinase (MAPK) pathway mutations, such as BRAF V600K, NRAS G12/G13, or KIT mutations, or inactivation of the negative regulators of Ras, such as NF1 or RASA2." (PMID 38396984, 2024). "However, the role of miR-708 in melanoma and acute myeloid leukemia (AML) has yet to be characterized, and whether the expression of NRAS, one of the most important oncogenes in these cancers, is targeted by miR-708 remains unknown." (PMID 37083947, 2023). "However, MALAT1-inhibition did not significantly affect NRAS RNA levels in NRAS-mutant melanoma cells." (PMID 37235843, 2023). "Moreover, to date, the contribution of DDR1 to NRAS-driven melanoma growth and MEKi resistance has not been investigated." (PMID 36765910, 2023). "Thus, the data in this study provide the rationale for testing the use of drugs targeting ABL1/2 and DDR1 in combination with MEKi for patients with NRAS-mutant melanomas who have failed to respond to immunotherapy." (PMID 36765910, 2023). "Thus, p38 levels do not influence beta-catenin in NRAS-mutant melanoma cells and beta-catenin mostly remains localized in the nucleus." (PMID 36765834, 2023). "Unlike melanomas harboring BRAF mutations, which are highly sensitive to MAPK inhibition (BRAF and MEK inhibitors; BRAFi, MEKi), BRAFi treatment of melanomas harboring wild-type BRAF (including NRAS-mutant) activates MEK/ERK and increases melanoma growth." (PMID 36765910, 2023). "However, a phase II study investigating the combination in BRAF/NRAS wild-type, and NRAS-mutant melanoma patients (NCT01941927) revealed no improvement to overall or progression-free survival." (PMID 37181747, 2023). "Collectively, we demonstrated the invasion tendency of NRAS-mutant melanoma cells in 2D assays and 3D spheroids, including the assessment of bona fide markers of invasion in melanoma cells, and found that p38 does not increase invasion in NRAS-mutant melanoma cells." (PMID 36765834, 2023). "However, two similar reports have indicated that BRAF but not CRAF plays a critical role in initiating NRAS-driven melanoma, even though both display compensatory functions in tumor progression." (PMID 38111008, 2023). "In contrast to BRAF and NRAS, KIT mutations do not associate with histological subtypes or tumour stage; they do, however, have a close association with increasing age, acral mucosal subtypes of melanoma, and chronic sun-induced damaged sites." (PMID 36232957, 2022). "However, there is no targeted drug for mutant NRAS, hence in the case of NRAS mutant melanomas the current approaches are largely concentrated on downstream signalling pathways such as using MEK-targeted inhibitors." (PMID 35379799, 2022). "Melanoma may arise from single melanocytes or clusters of melanocytes known as naevi, with or without BRAF or NRAS mutation." (PMID 35740696, 2022).